SCYL1 (SCY1 like pseudokinase 1)
Description:
Regulates COPI-mediated retrograde protein traffic at the interface between the Golgi apparatus and the endoplasmic reticulum. Involved in the maintenance of the Golgi apparatus morphology. [Isoform 6]: Acts as a transcriptional activator. It binds to three different types of GC-rich DNA binding sites (box-A, -B and -C) in the beta-polymerase promoter region. It also binds to the TERT promoter region.
Synonyms: GKLP; NTKL; TAPK; TEIF; TRAP; HT019; P105; NKTL; MGC78454; SCAR21
Tractability: PROTAC: ubiquitination databases record sites on it; its protein half-life has been measured.
Gene: Protein-coding gene on chromosome 11 (65,525,072 to 65,538,711, forward strand). Ensembl gene ENSG00000142186.
Subcellular location: Cytoplasm, cytoskeleton, microtubule organizing center, centrosome; Endoplasmic reticulum-Golgi intermediate compartment; Golgi apparatus, cis-Golgi network; Cytoplasm (Isoform 1); Cytoplasm (Isoform 2); Cytoplasm (Isoform 3); Nucleus (Isoform 6)
Subcellular location (Human Protein Atlas): Cytosol
Gene Ontology:
Molecular function: cadherin binding; protein binding; ATP binding; protein kinase activity
Biological process: retrograde vesicle-mediated transport, Golgi to endoplasmic reticulum
Cellular component: cis-Golgi network; COPI vesicle coat; cytosol; endoplasmic reticulum-Golgi intermediate compartment; Golgi apparatus; membrane; cytoplasm; centrosome; nucleus
Genetic constraint (gnomAD): Loss-of-function variants: 85 observed, 87.94 expected, observed/expected ratio (o/e) 0.97, 90% interval 0.81 to 1.16. The upper end of that interval is the gene's LOEUF score, 1.16, which puts it in group 5 of 6, group 1 being the genes least tolerant of losing a copy. Missense variants: 963 observed, 1,060.7 expected, observed/expected ratio (o/e) 0.91, 90% interval 0.86 to 0.96. Synonymous variants: 458 observed, 425.97 expected, observed/expected ratio (o/e) 1.08, 90% interval 1 to 1.16.
Homologues: Orthologues: chimpanzee SCYL1 (99% identical), dog SCYL1 (92% identical), pig SCYL1 (92% identical), mouse Scyl1 (90% identical), rat Scyl1 (90% identical), guinea pig SCYL1 (90% identical), tropical clawed frog scyl1 (66% identical), Drosophila melanogaster yata (47% identical), Caenorhabditis elegans scyl-1 (34% identical). Paralogues in human: SCYL2 (19% identical), SCYL3 (19% identical).
Diseases named in the same sentence as SCYL1 in open-access papers:
SCYL1 is named in the same sentence as 49 diseases in open-access papers, as found by Europe PMC text mining. Sharing a sentence is not in itself a finding about the gene and the disease. The quoted sentences say what the papers report.
Ataxia (6 papers, 2009 to 2025). Ataxia refers to impaired coordination of voluntary muscle movement. "In human mutations in SCYL1 were associated to peripheral neuropathy, cerebellar atrophy, and ataxia." (PMID 33753324, 2021). "In humans, recessive mutations in SCYL1 resulting in complete loss of the protein were identified in two unrelated families with a similar syndrome characterized by liver failure, peripheral neuropathy, cerebellar atrophy, and ataxia." (PMID 40243816, 2025).
liver failure (5 papers, 2018 to 2025). A liver disease characterized by the liver losing or has lost all of its function. "Mutations of SCYL1 in humans are associated with a variety of disorders, including neurodegeneration, intellectual disabilities, and liver failure." (PMID 32314960, 2020). "Mutations or knockout mammalian SCYL1 may cause neural degeneration, intellectual disabilities, and liver failure, but the underlying mechanisms are unclear." (PMID 32314960, 2020).
acute liver failure (4 papers, 2018 to 2025). Rapid deterioration of liver function causing encephalopathy and coagulopathy. "Biallelic pathogenic variants in SCYL1 were first described in three human individuals in 2015 causing recurrent acute liver failure, spinocerebellar ataxia and peripheral neuropathy." (PMID 41063534, 2025). "We aimed to identify patients with SCYL1 variants within an exome-sequencing study of individualswith infantile cholestasis or acute liver failure of unknown etiology." (PMID 29419818, 2018).
cholestasis (3 papers, 2018 to 2023). Impairment of the bile flow caused by obstruction within the liver, or outside the liver in the bile duct system. "In conclusion, biallelic variants in SCYL1 can cause recurrent infantile cholestasis with a variableneurological phenotype." (PMID 29419818, 2018). "Variants in SCYL1 were identified using exome sequencing in individuals with infantile cholestasis or acute liver failure of unknown etiology." (PMID 33557414, 2021). "The mechanism via which SCYL1 variants cause cholestasis remains to be determined." (PMID 33557414, 2021). "SCYL1 deficiency may lead to apredominant cholestatic phenotype with variable neurological features, which wesuggest to name CALFAN syndrome (low γ-glutamyl-transferase cholestasis, acute liverfailure, and neurodegeneration)." (PMID 29419818, 2018). "Because the recurrent cholestasis in patients with CALFAN syndrome is triggered by fever episodes, it is possible that the SCYL1 variants reflect temperature-sensitive mutations that impair SCYL1 protein function at non-permissive higher temperatures." (PMID 33557414, 2021).
amyotrophic lateral sclerosis (2 papers, 2017 to 2021). Amyotrophic lateral sclerosis (ALS) is a neurodegenerative disease characterized by progressive muscular paralysis reflecting degeneration of motor neurons in the primary motor cortex, corticospinal tracts, brainstem and spinal cord. "In mice, loss of SCYL1 function leads to an early onset motor neuron disorder with characteristic features of amyotrophic lateral sclerosis (ALS), including mislocalization of TDP43 and ubiquilin-2 in cytoplasmic aggregates in spinal motor neurons." (PMID 28570664, 2017).
breast carcinoma (2 papers, 2022). "The results have shown that SCYL1 is overexpressed in breast cancer, and the expression of SCYL1 is associated with poor clinical outcomes of breast cancer patients." (PMID 36290821, 2022). "Association of SCYL1 with prognosis of breast cancer was determined based on the PrognoScan database." (PMID 36290821, 2022). "In conclusion, our findings indicate that SCYL1 is overexpressed in breast cancer and expression of SCYL1 is associated with poor prognosis of breast cancer." (PMID 36290821, 2022). "In addition, SCYL1 has been linked to breast cancer progression, but its precise oncogenic function is disputed." (PMID 35948564, 2022). "The impact of SCYL1 expression to survival data was evaluated using the PrognoScan database, we found high expression of SCYL1 was associated with worsened prognoses in breast cancer patients as measured by overall survival (OS), disease special survival (DSS), and relapse free survival (RFS)." (PMID 36290821, 2022). "We used the lentiviral shRNA plasmid vector that knockdown SCYL1 to study the role of SCYL1 in breast cancer cell lines." (PMID 36290821, 2022). "We also examined the expression of SCYL1 in 247 breast cancer tissues with immunohistochemical (IHC) staining." (PMID 36290821, 2022). "Then, the PrognoScan database was employed to assess the prognostic significance of SCYL1 in breast cancer." (PMID 36290821, 2022). "According to the TMA assay, the results showed that 154/247 breast cancer patients (62.3%) were strongly stained with anti-SCYL1, and 93 tumor samples (37.7%) had weak or no staining." (PMID 36290821, 2022). "Next, we carried out the transwell migration assay to determine the effect of SCYL1 knockdown on breast cancer cell migration in both shSCYL1 cell lines." (PMID 36290821, 2022). "The expression of SCYL1 in breast cancer was significantly increased compared with that of the paracancer normal tissues." (PMID 36290821, 2022). "Particularly, the SCYL1 expression in patients with BRAC breast cancer was detected in TCGA database." (PMID 36290821, 2022). "Based on these results, we inferred that silencing endogenous SCYL1 expression can suppress the migration of breast cancer cell lines MDA-MB-231 and MCF-7." (PMID 36290821, 2022). "Both the bioinformatics results and IHC staining results of our in-house cases suggested SCYL1 is significantly higher expressed in patients with breast cancer." (PMID 36290821, 2022). "Our studies clearly indicate that SCYL1 functions in progression of breast cancer; it is possible that SCYL1 promotes tumorigenesis of breast cancer via regulating vesicle trafficking and structure of Golgi." (PMID 36290821, 2022). "Our initial study identified SCYL1 as a putative mTORC1-responsive protein in epithelial MCF-7 breast cancer cells." (PMID 35948564, 2022). "Further study is needed to better understand the mechanisms by which SCYL1 regulates breast cancer progression." (PMID 36290821, 2022). "Through mining TCGA datasets data, hyperexpression of SCYL1 was observed in breast cancer tissues compared with adjacent normal tissues." (PMID 36290821, 2022). "In this study, we determined expression of SCYL1 in breast cancer by searching the Cancer Genome Atlas (TCGA) and Tumor Immunoassay Resource (TIMER) databases." (PMID 36290821, 2022). "The transwell migration and wound healing assays showed that downregulation of SCYL1 in breast cancer cells impaired their abilities in migration." (PMID 36290821, 2022). "Taken together, our data suggest that SCYL1 is a biomarker for poor prognosis of breast cancer, has a promoting role in breast cancer progression, and is a potential target for breast cancer therapy." (PMID 36290821, 2022). "Subsequently, we investigated whether SCYL1 expression was correlated with prognosis in breast cancer patients." (PMID 36290821, 2022). "These IHC results confirmed that SCYL1 is upregulated in breast cancer." (PMID 36290821, 2022).
breast carcinoma (continued). "Furthermore, knockdown of SCYL1 by shRNAs significantly inhibited the proliferation and migration of breast cancer cells." (PMID 36290821, 2022). "Up to now, studies on the role of SCYL1 in breast cancer progression are still rare." (PMID 36290821, 2022). "In addition, knockdown of SCYL1 dramatically inhibits proliferation and migration of breast cancer cells, suggesting a promoting role of SCYL1 in breast cancer progression." (PMID 36290821, 2022). "Downregulation of SCYL1 in breast cancer cells severely inhibits cell proliferation." (PMID 36290821, 2022). "Moreover, we performed in vitro experiments to evaluate the effects of SCYL1 on breast cancer cell proliferation and migration." (PMID 36290821, 2022). "The average IHC staining score of SCYL1 in the breast cancer tumor tissues is 3.77 ± 3.21, compared to the score of normal tissues at 1.93 ± 57.75, indicating that expression of SCYL1 in the breast cancer tumors is significantly higher than in their adjacent normal tissues (p < 0.0001)." (PMID 36290821, 2022). "Therefore, this study aims to investigate whether SCYL1 is abnormally expressed in breast cancer and affects the behavior of breast cancer cells, in order to evaluate the value of SCYL1 in the prognosis of this disease." (PMID 36290821, 2022). "Here, we characterize the N-terminal kinase-like protein SCYL1 as a Golgi-localized target through which mTORC1 controls organelle distribution and extracellular vesicle secretion in breast cancer cells." (PMID 35948564, 2022). "However, the role of SCYL1 in human breast cancer progression remains largely unknown." (PMID 36290821, 2022).
triple-negative breast carcinoma (2 papers, 2017 to 2022). An invasive breast carcinoma which is negative for expression of estrogen receptor (ER), progesterone receptor (PR), and human epidermal growth factor receptor 2 (HER2). "It has been shown that SCYL1 cooperates with TEX14 and PLK1 to constitute the oncogenic signaling STP axis, which promotes triple-negative breast cancer through downregulation of the tumor suppressor REST." (PMID 36290821, 2022). "A recent study identified SCYL1 as one of the components of the oncogenic STP axis, which promotes triple-negative breast cancer by regulating degradation of the REST tumor suppressor." (PMID 28570664, 2017). "Our studies, however, do not contest the possible role of Tex14 in mediating REST turnover; the formation of an STP complex; or the possibility of SCYL1, Tex14, PLK1, and REST being aberrantly expressed in triple-negative breast cancer cells." (PMID 28570664, 2017).
breast tumor (1 paper, 2022). "Meanwhile, we collected breast tumor tissue samples from 247 cases and detected expression of SCYL1 in the tumors using the tissue microarray assay (TMA)." (PMID 36290821, 2022).
glioblastoma multiforme (1 paper, 2022). "Nevertheless, SCYL1 expression was significantly reduced in GBM (glioblastoma multiforme) and PCPG (pheochromocytoma and paraganglioma) than in normal controls." (PMID 36290821, 2022).
neuroblastoma (1 paper, 2020). Neuroblastoma (NB) is the most common solid, extracranial childhood tumor. "Mutation of SCY1-like pseudokinase 1 (SCYL1) or neuroblastoma-amplified sequence (NBAS), which function in COPI vesicle traffic, can manifest in the liver, but typically also affect other tissues, and are discussed further in the ‘Multi-systemic disorders’ section below." (PMID 32433026, 2020).
neurodegenerative disease (5 papers, 2009 to 2023). A disorder of the central nervous system characterized by gradual and progressive loss of neural tissue and neurologic function. "CALFAN syndrome is an extremely rare disease consisting of recurrent pediatric acute liver failure (PALF), neurodegenerative diseases, and skeletal abnormalities associated with SCYL1 gene mutation." (PMID 37554250, 2023).
cancer (4 papers, 2016 to 2025). A tumor composed of atypical neoplastic, often pleomorphic cells that invade other tissues. "Early study has showed that centrosomal localization of SCYL1 is associated with centrosome amplification and telomere dysfunction, suggesting SCYL1 is likely to play a role in cancer development." (PMID 36290821, 2022). "In order to explore the discrepancies of SCYL1 expression in human cancers, the SCYL1 expression in different tumors and normal tissues of multiple cancer types were analyzed using the RNA-seq data in TCGA database through the TIMER2.0." (PMID 36290821, 2022). "Our findings indicate that mTORC1 and SCYL1 might regulate EV secretion in a previously unanticipated role in cancer progression." (PMID 35948564, 2022). "Currently, little is known about the role of SCYL1 in cancer progression and metastasis." (PMID 36290821, 2022). "It is notable therefore that the control of phosphorylation at the sites in SCYL1, that are equivalent to those identified in fission yeast Ppk32, would be predicted to reduce SCYL1 protein levels and so increase cell death and treatment of cancer types with inherent Golgi stress." (PMID 27191590, 2016). "Whether the scaffolding functions of SCYL1 and its role in vesicle trafficking and secretion might affect cancer progression is not known." (PMID 35948564, 2022).
peripheral neuropathy (4 papers, 2018 to 2025). A disorder affecting the peripheral nervous system. "Although nerve conduction studies were not performed, the diminished deep tendon reflexes suggested the presence of an underlying peripheral neuropathy, similar to the patients in the first report of AMC4 as well as patients with SCYL1 loss of function." (PMID 40243816, 2025).
tumor (4 papers, 2015 to 2025). "Moreover, SCYL1 is significance highly expressed in tumor tissues, when compared to normal tissues in LAML (p = 6.8 × 10−17)." (PMID 40699783, 2025). "IHC staining of 247 BC tumor samples has shown that SCYL1 was overexpressed in 62.3% of BC tumors." (PMID 36290821, 2022). "In our studies, the major role of SCYL1 seems promoting BC tumor cell proliferation and migration, whether SCYL1 promotes BC through degradation of the REST warrants further investigations." (PMID 36290821, 2022). "In this study, we first observed the expression of SCYL1 is elevated at mRNA levels in 14 types of tumor tissues, suggesting that SCYL1 might be an important pro-oncogenic protein in these tumor types." (PMID 36290821, 2022).
SCYL1 also shares sentences with these, for which no sentence is quoted: Cerebellar atrophy (6 papers); colorectal cancer (2); genetic disease (2); infection (2); lung squamous cell carcinoma (2); Alzheimer disease (1); breast invasive carcinoma (1); Cerebral ischemia (1); cholangiocarcinoma (1); colon adenocarcinoma (1); developmental delay (1); Encephalopathy (1); esophageal carcinoma (1); Gait ataxia (1); head and neck squamous cell carcinoma (1); hematological cancers (1); hepatopathy (1); Intellectual disability (1); kidney chromophobe (1); lung adenocarcinoma (1); lung carcinoma (1); microcephaly (1); Neurodegeneration (1); neuropathy (1); paraganglioma (1); pheochromocytoma (1); polyneuropathy (1); prostate adenocarcinoma (1); schizophrenia (1); skeletal dysplasia (1).
A further 5 diseases each share a sentence with SCYL1 in 1 paper.